IL17A (interleukin 17A)
Diseases named in the same sentence as IL17A in open-access papers (continued):
Sharing a sentence is not in itself a finding about the gene and the disease.
psoriasis (continued). "Our study revealed increased transcripts levels of IL17A, IFNG, and FOXP3 in moderate-severe psoriasis patients." (PMID 28042206, 2016). "Brodalumab is a monoclonal antibody that targets and blocks the signalling pathway of interleukin receptors (IL17A, IL17F and IL23), which has been proven effective for psoriasis treatment." (PMID 26892034, 2016). "Treg to Th17 transition in psoriasis is driven by IL-23 signalling, and triple-positive CD4+/Foxp3+/IL-17A+ cells can be found in skin lesions." (PMID 26583100, 2015). "Positive cells to both Th17 and Treg populations (IL-17A+/Foxp3+/CD4+) have been found in CD18low P/J mouse and in skin lesions from patients with severe psoriasis." (PMID 26136626, 2015). "Previously, in a phase II study in patients with recalcitrant psoriasis, treatment with apremilast 20 mg BID led to significant decreases in proinflammatory gene expression in the lesional skin, including IL-12/IL-23p40, IL-17A, and IL-23p19." (PMID 25973439, 2015). "Cytokines activate inflammatory and proliferative cascades in psoriasis lesions, as evidenced by the effectiveness of treatments directed against TNF, IL-17A and IL-23." (PMID 25883770, 2015). "In addition, keratinocytes in psoriasis as well as synoviocytes in RA are capable of responding to direct IL-36 ligands stimulation with production of IL-6, IL-8, and antimicrobial peptides, which cooperate with IL-17A and TNF-alpha promoting neutrophil activation and migration." (PMID 25126586, 2014). "Our attempt to model skin inflammation showed that the combination of IL-17A, IL-22, IL-1α, OSM and TNFα (Mix M5) synergistically increases chemokine and antimicrobial-peptide expression, recapitulating some features of psoriasis." (PMID 25010647, 2014). "In contrast to psoriasis, reduced levels of IFN-γ and IL-17A have been reported in atopic dermatitis." (PMID 23555696, 2013). "This combination was more effective in inducing RNase 7 than the combination of IL-17A/TNF-α, a combination previously identified as a strong inducer of psoriasis-related immune response genes including several AMP." (PMID 23555696, 2013). "Although psoriasis was initially classified as a Th-1-polarized disease, a clear role for CD4+ T cells that produce IL-17A and IL-22 (Th-17 and Th-22 cells) has been established in recent years, primarily at lesional sites, but also in the blood." (PMID 23468834, 2013). "For CD8+ T cells, we observed that the production of IL-17A, IL-22, IFN-gamma, TNF-alpha, and IL-2 were higher in lesional skin than unaffected skin of psoriasis patients." (PMID 23468834, 2013). "Many immune-derived cytokines, including IL-23, IL-17A, IL-20, IL-22, IL-1β, IL-6, and TNF-a, are involved and interact as a network in the pathogenesis of psoriasis." (PMID 23825622, 2013). "We demonstrated that psoriasis-related transcripts, such as IFN-γ, TNF-α, IL-17A, CCL20, IL-23, IL-6, IL-1α and IL-22, were significantly enhanced in mouse ears treated with PL and rMCP-1 than those with 1×PBS control." (PMID 21311769, 2011). "IL-17A, which is known to be a very potent inducer of HBD2, is a central cytokine in psoriasis pathogenesis and correlates with disease severity." (PMID 19623255, 2009). "IL-17E promotes keratinocyte proliferation, differentiation (keratin 10), and motility in psoriasis, distinct from IL-17A, with no antimicrobial effects, indicating its key role in epidermal pathophysiology." (PMID 40536951, 2026). "Therapeutics such as Anakinra (IL-1R antagonist), Tocilizumab (anti-IL-6 receptor), Secukinumab (anti-IL17A), and Belimumab (anti-B-cell activating factor) are routinely used in a variety of inflammatory diseases such as gout, SLE, psoriasis, Crohn’s disease, and RA." (PMID 41503139, 2025). "In psoriasis, chronic inflammation, particularly mediated by IFN-γ, IL-17A, and IL-22, may override any anti-proliferative effect of EPPK1 loss." (PMID 40746860, 2025).
psoriasis (continued). "Similarly, human Vγ2Vγ9 cells have been observed to produce inflammatory mediators such as IFN-γ, IL-17A, TNF-α, CCL3, -4, -5, -6, which are present in psoriasis and aim to recruit immune cells to the skin and stimulate keratinocytes." (PMID 40276509, 2025). "Further validation by RT-PCR confirmed that IL-23 directly acted on macrophages, promoting the levels of IL-17A, IL-17F, IL-22, and IFN-γ, which may contribute to the severity of psoriasis in mice." (PMID 41383588, 2025). "Previous studies have demonstrated elevated IL-17A expression in the lesional skin and serum of AGEP patients, suggesting that IL-17A may represent a common downstream mediator between AGEP and psoriasis." (PMID 41346610, 2025). "This case also indicates that IL-17A may play a pivotal role in the pathogenesis of both AGEP and psoriasis." (PMID 41346610, 2025). "Notably, the module score also incorporated proinflammatory cytokines (IL17A, IL1B, IL22, IL23, and IFNG) which were upregulated in lesional psoriasis, providing context for the regulation of plakin family members." (PMID 40746860, 2025). "The integration of docking and DFT results highlights the novelty of this study, as E. neriifolia phytochemicals have not been extensively explored against IL‐17A compared to other medicinal plants studied for psoriasis." (PMID 41416116, 2025). "In early studies, oral RORγt inhibitor VTP-43742 has demonstrated a reduction in Psoriasis Area and Severity Index (PASI) scores and a decrease in circulating IL-17A and IL-17F levels, indicating its potential in managing moderate to severe plaque psoriasis in patients." (PMID 41301460, 2025). "Similarly, in a mouse model of psoriasis using imiquimod (IMQ), depression-like symptoms were observed alongside IL-17A induction, and treatment with an anti-IL-17A antibody led to a reduction in IMQ-induced depression-like behaviors." (PMID 40469524, 2025). "Subsequent treatment with the interleukin (IL)-17a inhibitor secukinumab did not improve the psoriasis and led to a recurrence of the osteomyelitis." (PMID 40475785, 2025). "The aim of the present study is to perform an in-depth immunological characterization of patients with moderate-to-severe psoriasis treated with secukinumab, an IL-17A inhibitor, stratified by super responder (SR) and non-super responder (NSR) status." (PMID 40650209, 2025). "In addition, in the psoriasis group induced by IMQ, the levels of IL-1β, IL-6, TNF-α, and IL-17A were higher in the cko group than those in the wt group, especially IL-1β and IL-6 (p < 0.05)." (PMID 40430037, 2025). "IL-17A has been extensively studied in autoantibody-mediated disease and classical chronic inflammatory diseases, such as neuromyelitis optica (NMO), rheumatoid arthritis, ankylosing spondylitis, and psoriasis." (PMID 40150012, 2025). "In addition to psoriasis, ILC3-produced IL-17A also increases IL-33 secretion from KCs, which induces type 2 immune responses and leads to the progression of atopic dermatitis." (PMID 41467015, 2025). "Furthermore, in an in vitro psoriasis model where normal keratinocytes were stimulated with the M5 cytokine cocktail (TNF-α, IL-17A, IL-22, IL-1α, and oncostatin M), DGAT2 expression was similarly reduced." (PMID 40694426, 2025). "Increased IL-17A levels were found in RA, SLE, and psoriasis patients." (PMID 40821838, 2025). "Consequently, this research provides valuable insights into the binding ability of phytoconstituents of VT oil against IL-17A and TNF-α, paving the way for the development of novel drugs for the treatment of psoriasis." (PMID 40892753, 2025). "In the IMQ-induced psoriasis mouse model, this approach reduced epidermal thickness, inhibited infiltration of CD3+ T cells and CD4+ T cells, lowered serum IL-17A and IFN-γ levels, and normalized spleen indices, demonstrating systemic anti-inflammatory effects." (PMID 41226338, 2025).
psoriasis (continued). "When psoriasis-like dermatitis was induced in wild-type (WT) mice and Sema4A knockout (KO) mice by imiquimod (IMQ) application on ears, ear swelling on day 4 was more pronounced in Sema4A KO mice with upregulated Il17a gene expression." (PMID 39737847, 2024). "Interestingly, incubation of 3D full-thickness skin models with recombinant human IL-17A, IL-22 and TNF-alpha for 5 days leads to hyperkeratosis and parakeratosis, both characteristic of psoriasis." (PMID 37707681, 2024). "In mice with hyperlipidemic serum, increased IL-6 production by CD1b + DCs and IL-17A secretion by HJ1 T cells were observed, indicating that the potential link between hyperlipidemia and psoriasis might lie in self-lipid-reactive T cells." (PMID 38347543, 2024). "This highlights the role of the skin microbiome in psoriasis onset or exacerbation as it has been demonstrated that γδ T cells are capable of secreting IL-17A in the absence of IL-23 stimulation." (PMID 39459406, 2024). "Furthermore, we examined a set of inflammatory cytokines, including IL-17A, IL-23A, IL-1β, TNF-α, IL-6, and IL-22, at the mRNA level in LPS-induced psoriatic keratinocytes, which are closely related to psoriasis in vivo." (PMID 39109246, 2024). "Patients received treatment with anti-IL-4RA or anti-IL-13 (anti-Th2), anti-IL23 or anti-IL-17A (Anti-Th17), or JAK1 inhibitors (with the ability to target Th1) based on their diagnosis of AD, psoriasis, or LP established by clinical and histopathology criteria." (PMID 39695162, 2024). "Although IL-17A plays a significant role in psoriasis, the correlation between abnormal metabolic LCFAs and IL-17A in psoriasis patients has not yet been established." (PMID 38185620, 2024). "Additionally, the serum lipidomic of LCFAs in IMQ-treated WT and Tcrd−/− mice further supported the correlation between IL-17A and abnormal LCFA metabolism in psoriasis patients." (PMID 38185620, 2024). "In addition, psoriasis related proinflammatory mediators such as TNF‐α, IL‐1β, IL‐17A, and IFN‐γ can induce endoplasmic reticulum stress in a variety of immune cells." (PMID 38174774, 2024). "However, after receiving anti-IL-17A mAb treatment, the LCFA contents in the serum of psoriasis patients approached those of healthy volunteers." (PMID 38185620, 2024). "On the other hand, focusing on IL-17A-producing cells, the proportion of IL-17A-producing Vγ2 and DNγδ T cells in CD3 fraction in the epidermis was significantly higher in Sema4A KO mice, consistent with the results from IMQ-induced psoriasis-like dermatitis." (PMID 39737847, 2024). "Notably, while in healthy skin IL-17A is produced mainly by CD4+ T cells and IFN-γ is produced predominantly by CD8+ T cells, in psoriasis, both CD4+ T cells and CD8+ T cells co-produce both IL-17A and IFN-γ." (PMID 38642273, 2024). "Moreover, FCGR3A was found to interact with known therapeutic targets of psoriasis such as CD2, Tumor necrosis factor (TNF), Integrin subunit alpha L (ITGAL), and IL17A." (PMID 39883516, 2024). "After IL-17A inhibitor treatment in Psoriasis patients, longitudinal studies observed a trend toward a normal distribution of the gut microbiome and modulation of apoptosis-related metabolic pathways." (PMID 38482003, 2024). "In IMQ-induced psoriasis skin, both S1pr2-/- and S1pr2fl/fl K14-Cre mice showed higher expressions of proinflammatory cytokines such as TNF-α, IL-17A, and IL-1β together with higher expressions of MyD88/NF-κB pathway compared to the wild-type mice." (PMID 39391307, 2024). "The possible mechanistic relationship between IL‐17A and its impact on depression symptoms in psoriasis patients has not been elucidated." (PMID 39660880, 2024). "The oxidative stress model of HaCaT psoriasis was established by TNF-α and IL-17A in vitro." (PMID 38799436, 2024).
psoriasis (continued). "Bimekizumab treatment completely reversed the levels of cytokines/chemokines, anti‐microbial peptides, or proliferation‐related molecules, such as CXCL8, CCL20, IL‐17A, IL‐17F, IL‐17C, keratin 16, IL‐36γ, DEFB4, or S100A7, in psoriasis lesional skin to the levels of non‐lesional skin." (PMID 38482898, 2024). "Since γδ T cells have been shown to secrete IL-17A without IL-23 activation, this emphasizes the significance of the skin microbiome in the initiation or exacerbation of psoriasis." (PMID 39408916, 2024). "Psoriasis pathogenesis involves multiple immune cells (leukocytes, macrophages, neutrophils, keratinocytes, and T cells) releasing proinflammatory factors like IL-1, IL-6, tumor necrosis factor (TNF)α, IL-17A, IL-22, and IL-23." (PMID 39408568, 2024). "Furthermore, the study indicated a potential correlation between IL-17A and abnormal LCFA metabolism in psoriasis patients, which was supported by the alterations in serum LCFAs observed in IMQ-treated WT and Tcrd−/− mice." (PMID 38185620, 2024). "Currently, although biologics targeting TNF-α, IL-12/IL-23 or IL-17A are highly effective in the treatment of psoriasis, not all patients respond in the same manner." (PMID 38566145, 2024). "As murine models of human disease have to be considered cautiously, further corroboration of our data in additional murine psoriasis models independent of topical treatment or IL-17A overexpression is needed." (PMID 38127137, 2024). "While, it is not clear if psoriasis‐induced systemic IL‐17A increase can mediate the neuronal inflammation and result in depressive‐like symptoms." (PMID 39660880, 2024). "The signature also correlated with the high levels of IL-26 protein, but not with the expression levels of IL-17A in the lesions, indicating that IL-26 represents a key driver of autoinflammation in psoriasis and pustular disease activity." (PMID 38448036, 2024). "In psoriasis lesions, forkhead box transcription factor P3 (FOXP3)-positive regulatory T (Treg) cells can differentiate into highly pro-inflammatory, triple-positive IL-17A+/FOXP3+/CD4+ Th17 cells, thereby sustaining the overall inflammatory process." (PMID 39684717, 2024). "Here, we investigated the expression of psoriasis-related cytokines (TNF-α, IL-6, IL-22, IL-23, IL-17A, IL-17E, IL-17F, IL-4 and IL-10) in the inflamed skin after mannan exposure at the peak (day 4) and the end (day 7) of psoriasis with/without inhibitor(s) treatment." (PMID 38444844, 2024). "Moreover, research indicates that IL-17A- and IL-22-producing resident memory T cells (TRM) are enriched in the affected tissues of psoriasis patients, suggesting that these cells contribute significantly to the recurrence of the disease." (PMID 39684717, 2024). "Therapeutic targeting of IL17A and IL21 has been evaluated in clinical trials for a variety of inflammatory and autoimmune indications, and anti-IL17A monoclonal antibodies were recently approved for psoriasis." (PMID 38609465, 2024). "The correlation between psoriasis and atherosclerosis has been conceptualized as “one syndrome and two plaques” based on the analogous inflammatory cytokine profiles shared by both conditions, such as TNF-α and IL-17A." (PMID 39104857, 2024). "Daphnetin treatment inhibits the proliferation and inflammatory response of human HaCaT keratinocytes and ameliorates imiquimod (IMQ)-induced psoriasis-like skin injury in mice and attenuates the IMQ-induced upregulation of inflammatory cytokines, including IL-6, IL-23A, and IL-17A." (PMID 39544933, 2024). "When compared with secukinumab, an IL-17A inhibitor, in the ECLIPSE trial, a significantly greater proportion of patients with moderate-to-severe psoriasis treated with guselkumab achieved the primary endpoint of at least 90% improvement in PASI (PASI 90) at week 48 (84 vs 70%; P <.0001)." (PMID 39224116, 2024).
psoriasis (continued). "In psoriasis-like dermatitis models induced by IMQ, adopting a Western diet for a brief four-week period has been shown to boost the population of γδ T cells producing IL-17A, and to elevate the activity levels of the IL-23 receptor." (PMID 38035065, 2023). "Although anti-IL-17A monoclonal antibody does not directly target IL-17F, systemic IL-17A blockade also removed 95% of IL17F-expressing T-cells in psoriasis skin, potentially mediated by IL-23 reduction in dendritic cells." (PMID 37781383, 2023). "Furthermore, they postulated that PCSK9 is connected with a higher atherosclerotic burden in psoriasis patients, and, using blood transcript analysis, they identified TNF, IL6, IL17A, and IL23 as PCSK9-related pathways." (PMID 37234169, 2023). "While head-to-head trials have shown dual blockade of IL-17A and IL-17F to be superior to biologic targeting IL-17A, IL-12/23, TNF-α in patients with psoriasis, further data is required to confirm whether this finding replicated in patients with PsA." (PMID 37731935, 2023). "Furthermore, we detected a similar upregulation of the IL-36 signaling pathway in psoriasis-like skin lesions of mice that either develop psoriasis upon IMQ treatment, or in psoriatic mice that overexpress IL-17A in the epidermis." (PMID 38162658, 2023). "In addition, T cells expressed IL17A, IL17F, and IL22 that, coupled with their receptors expressed by myeloid cells and keratinocytes, are known to promote inflammation in psoriasis." (PMID 37308489, 2023). "Moreover, AOA decreased IL-17A, RORC, and IL-22 secretion by Th17 cells, confirming that AOA is effective in the immune regulation of psoriasis." (PMID 37649889, 2023). "Following excellent efficacy secukinumab has shown in clinical trials, two other humanized monoclonal IL-17A antibodies ixekizumab and netakimab, and an IL-17A receptor antagonist brodalumab, gained FDA approval for treatment of psoriasis and axial spondiloarthritis." (PMID 37427128, 2023). "Currently, biologics targeting TNF-α, IL-12/IL-23 p40, IL-23p19, IL-17A, and IL-36R are used in the clinical treatment of psoriasis, and they are superior in terms of efficacy than nonbiological treatment." (PMID 37762693, 2023). "In the damaged skin of psoriasis patients, low levels of GILZ were found, which is inversely correlated with the levels of IL-23, IL-17A, IL-22, and STAT3, key factors of Th17 lymphocytes, indicating the existence of a regulatory loop between GILZ and Th17 activity." (PMID 38067176, 2023). "Although guselkumab, a selective IL-23 inhibitor, and secukinumab and ixekizumab, monoclonal antibodies targeting IL-17A, were highly effective in treating psoriasis, their treatment results in IBD were not consistent." (PMID 36902001, 2023). "In a mouse model of imiquimod-induced psoriasis-like skin lesions, apigenin decreased erythema, scaling, and Psoriasis Area and Severity Index (PASI) score, and it also inhibited NF-kB activation and the IL-23/STAT3/IL-17A pathway." (PMID 38248322, 2023). "Patients with scalp, nail, or genital, but not palmoplantar or face/neck psoriasis, had significantly higher odds of achieving clearance at week 12 in the anti-IL-17A cohort compared to the other biologics cohort." (PMID 37457564, 2023). "However, in psoriasis, IL-36 induces the activation of the IL13/IL17A axis at the skin, contributing to the inflammatory process and, thus, to the severity of the disease." (PMID 37550362, 2023). "In psoriasis, IL-17A mainly acts on non-hematopoietic cells, especially epithelial cells, and continues to participate in the protective immunity of marginal tissues." (PMID 37373186, 2023). "Of great importance, the therapeutic agents currently used in the treatment of psoriasis, including retinoids, vitamin D3 analogues, dimethyl fumarate, narrow-band UVB and biologic drugs targeting subunit p19 of IL-23 and IL-17A, all have the effect of restoring the defected Tregs." (PMID 37892710, 2023).